NES (nestin)
Diseases named in the same sentence as NES in open-access papers (continued):
Sharing a sentence is not in itself a finding about the gene and the disease.
melanoma (60 papers, 2008 to 2025). A malignant, usually aggressive tumor composed of atypical, neoplastic melanocytes. "Overexpression of Nestin has been associated with advanced stages of melanoma, the invasion front and sites of melanoma metastases (see Ref." (PMID 38243233, 2024). "NES expression in melanoma has been associated with cell migration, invasion, disease progression, and metastasis." (PMID 39273022, 2024). "Upon reviewing the literature, it becomes apparent that certain markers, such as LOXL3, SNAI1, and NES, are associated with melanoma development." (PMID 39273022, 2024). "Reinstalling nestin expression in drug resistant BRAF mutated melanoma cells strongly impairs their migration and invasion ability." (PMID 38008717, 2023). "Downregulation of both vimentin and nestin has been previously linked to drug resistance in melanoma, as well as upregulation of processes such as PI3K/AKT signaling, remodeling of focal adhesions, actin cytoskeleton, and integrin signaling." (PMID 39086667, 2023). "Nestin expression is associated with cell migration and metastasis in prostate cancer, and tumor progression and deceased survival in melanoma." (PMID 29455657, 2018). "In addition, nestin downregulation in several melanoma cells lines was associated with the concomitant upregulation of matrix metalloproteinase‐1, ‐3, and ‐9." (PMID 35439345, 2022). "Interestingly, upregulation of MMP2 and MMP9 was linked with the depletion of nestin, a protein postulated as a melanoma stem cell marker, which was also observed in our research model." (PMID 31877948, 2019). "Nestin expression has been detected in malignant tumor tissues, and has been implicated in the development and metastasis of malignant tumors, such as brain malignancies, melanoma, colorectal, prostate, and pancreatic cancers." (PMID 25056574, 2014). "The reasons for the discrepancies in data are as follows: in melanoma, the depletion of nestin promotes tumor malignancy via a dual mechanism." (PMID 40799240, 2025). "In contrast, in melanoma, nestin expression has been primarily studied in melanoma cells rather than in CSCs." (PMID 40799240, 2025). "High expression levels of miR-21 correlate positively with nestin mRNA in Meningiomas, and suppression of miR-21 can reduce nestin expression, leading to decreased melanoma tumor growth." (PMID 40799240, 2025). "Somatic mutations in SOX10 occur in early-stage melanoma, with SOX10 upregulating MITF, MET, and Nestin expression in melanoma and responding to Wnt signals." (PMID 41012776, 2025). "The major point of our interest was to explore the co-expression of LOXL3, SNAI1, and NES in melanoma development and their supposed role in EMT." (PMID 39273022, 2024). "Concerning the mRNA expression, NES was expressed significantly higher in BRAF+ melanoma than in dysplastic nevus and melanoma in situ." (PMID 39273022, 2024). "In our study, we explored the potential role of LOXL3, SNAI1, and NES in melanoma progression and metastasis among patients with dysplastic nevi, melanoma in situ, and BRAF+ and BRAF− metastatic melanoma, using immunofluorescence and qPCR analysis." (PMID 39273022, 2024). "LOXL3, SNAI1, and NES are key factors in melanoma genesis, regulating tumor growth, metastasis, and cellular differentiation." (PMID 39273022, 2024). "NES was depicted as a reliable factor in prognosis melanoma metastasis, and a study demonstrated that reducing nestin expression decreases cell growth, migration, and invasion in human melanoma cells." (PMID 39273022, 2024). "Nestin staining was noticed as mild diffuse staining appearing sporadically in tumor cells of irregular nests of dysplastic nevus and melanoma in situ." (PMID 39273022, 2024). "To answer this point, we have evaluated the nestin prognostic value in TCGA public available melanoma dataset using the online software GEPIA, which uses the data deposited on The Cancer Genome Atlas (TCGA)." (PMID 38008717, 2023).
melanoma (continued). "First of all, nestin levels are lost in melanoma cells upon acquisition of targeted therapy resistance in contrast to miR-4443/miR-4488 that are up-regulated." (PMID 38008717, 2023). "Nestin is an intermediate filament present in neural progenitor cells, melanomas, and melanocytic nevi." (PMID 38132479, 2023). "Altogether these findings underscore not only a potential oncosuppressive role for nestin in BRAF-mutant melanomas but also unveil its potential as a predictive marker of clinical response to targeted therapy." (PMID 38008717, 2023). "It has to be mentioned that the oncosuppressive role of nestin in melanoma is challenged by different and contrasting studies that have reported an oncogenic role for this protein, not only in melanoma, but also in colorectal and hepatocellular carcinomas." (PMID 38008717, 2023). "To strengthen these observations, we have analyzed nestin protein levels by IHC in an internal cohort composed of 14 BRAF-mutant melanoma patients whose biopsies have been collected before starting targeted therapies." (PMID 38008717, 2023). "Altogether these data allowed to define nestin as novel molecular target of miR-4443/miR-4488 in melanoma." (PMID 38008717, 2023). "In this study, Nestin was confirmed to be the most reliable factor to prognose metastasis of melanoma as reported in previous papers." (PMID 35054386, 2022). "It was found that advanced patient age and immunohistochemical staining of Nestin and Fascin were statistically related to melanoma metastasis." (PMID 35054386, 2022). "This is the first study to report double immunofluorescent staining of Nestin and Fascin in melanoma." (PMID 35054386, 2022). "This is the first study that provides double immunofluorescence staining of Nestin and Fascin in melanoma." (PMID 35054386, 2022). "The aim of this study is to determine risk factors to predict metastasis in Japanese patients with Stage I or II melanomas by statistical analysis of clinical data and immunohistochemical staining of Nestin and Fascin." (PMID 35054386, 2022). "From these studies, the proteins, Nestin and Fascin, have been suggested to be involved with the process of melanoma metastasis." (PMID 35054386, 2022). "Nestin and Fascin are suggested to relate to melanoma metastasis, however, the potential role of Fascin is controversial." (PMID 35054386, 2022). "In conclusion, this study confirmed that Nestin is a useful factor to prognose metastasis with Stage I or II melanoma patients after the primary surgery." (PMID 35054386, 2022). "Nestin expression is observed in various embryonic cells and tissues, and a correlation of Nestin expression to clinical malignancy has been reported in melanoma and other tumors, such as breast cancer, ovarian cancer, and osteosarcoma." (PMID 35054386, 2022). "In this study, we found that treatment of melanoma cells with BCI, a DUSP1/DUSP6 inhibitor at a concentration close to IC50 for selective inhibition of DUSP1, caused upregulation of nestin and immature MAP2 in MAPKi-sensitive cells." (PMID 35999349, 2022). "Further studies on Nestin and Fascin in melanoma, other cancers and sarcomas with more cases are anticipated." (PMID 35054386, 2022). "Hong and Saint-Jeannet reported a positive relationship between nestin expression and advanced disease in several melanoma specimens; however, they observed high nestin expression in compound nevi." (PMID 35003391, 2021). "Experimental studies demonstrated the expression of nestin in several tumor cells like gastrointestinal stromal tumors, malignant melanoma, OSCC, pancreatic, prostate and breast cancers." (PMID 33507685, 2021). "More advanced studies have used a soft 3D gel to promote cancer properties and upregulate stem cell markers (i.e., CD133, nestin, c‐kit, and BMI‐1) in melanoma cells, suggesting that a 3D soft environment promotes CD133‐expressing tumor‐repopulating cells." (PMID 33717837, 2021).
melanoma (continued). "After lowering the Tβ4 level in melanoma cells, we observed an increased number of F-actin structures, along with Nestin and Vimentin’s location around the cell nucleus." (PMID 33807338, 2021). "In summary, the actin cytoskeleton, Nestin, and Vimentin filaments were organized significantly differently in melanoma cells with low Tβ4 levels than the cells with high TMSB4X expression." (PMID 33807338, 2021). "Nestin-expressing cells were detected in primary melanomas and metastases as well as in experimental lung metastases of NOD/SCID mice." (PMID 34943921, 2021). "Cancer stem cell properties of MACS-sorted CD133(+) BAK-P melanoma were previously verified by immunofluorescent staining and qRT-PCR analysis for stem cell markers, including Oct 3/4, Nestin, and ABCB5." (PMID 31623313, 2019). "Consistent with our 30 day in vivo phenotypic analysis, neuronal markers including Nestin, Tubb3, Gfap and Ngfr were upregulated in tumors, again a noted feature of human melanomas." (PMID 31685822, 2019). "Similar to the results in nude mice, Tomato+ cells in these tumors were positive for melanoma markers such as Sox10 and heterogeneously expressing melanocytic markers Dct and pigment, as well as neuronal markers Tubb3 and Nestin." (PMID 31685822, 2019). "Nestin and SOX2 are embryologic stem cell transcription factors that bind an enhancer region on the nestin gene, and they are preferentially co-expressed in metastatic melanomas when compared with nevi or primary melanomas." (PMID 29455657, 2018). "According to the literature, a high nestin expression was observed in 25% (14/56) of primary melanomas, 50% (84/165) of melanoma metastases and 40% (21/53) of melanoma cell lines." (PMID 26421614, 2015). "Self-renewing melanoma progenitor cells expressed nestin and both intermediate filament proteins nestin and vimentin were found to colocalize in melanoma." (PMID 26421614, 2015). "3D-MBs showed strong staining with antibodies against NOTCH and ID4, as well as NESTIN, a neural progenitor cell factor known to be variably expressed in 1205Lu cells and other melanoma cell lines." (PMID 25642713, 2015). "Similar expression patterns were observed in vessels of human melanoma samples: angiogenic vessels within the tumor were stabilized by Nestin(+) cells, whereas mature vessels in tumor-surrounding tissue down-regulated Nestin-expression." (PMID 25019063, 2014). "Immunohistochemistry of samples from patients showed intense FKBP51 nuclear signal and cytoplasmic positivity for the stem cell marker nestin in extravasating melanoma cells and metastatic brains." (PMID 23559012, 2013). "Nestin protein is most abundant at the infiltrating front of the tumors, suggesting that it plays important roles in melanoma cell migration and invasion." (PMID 22580387, 2012). "Various tumors show increased nestin expression, including central nervous system (CNS) tumors, melanomas, gastrointestinal stromal tumors (GIST), prostate cancer, breast cancer and pancreatic cancer." (PMID 22580387, 2012). "In malignant melanoma, stronger nestin expression is observed in advanced stage disease and in metastatic foci of melanoma cells." (PMID 22580387, 2012). "It has been suggested that nestin was an indicator of cell-dedifferentiation in melanocytes, as nestin protein was found to be abundant in melanoma." (PMID 21383848, 2011). "In human melanoma cells Sox9 has also been identified as an important regulator of Nestin expression." (PMID 21826226, 2011). "Spheroid cells derived from SLM8 expressed melanoma-associated markers integrin αvβ3 and CD146 (M-CAM), the neuroectodermal stem cells marker nestin, and the mesenchymal stem cells surface molecule CD166." (PMID 21526207, 2011). "Expression of nestin significantly increased in melanoma compared with nevi and correlates with more advanced stage of the disease." (PMID 22545195, 2010).
melanoma (continued). "For other tumors, nestin expression was still reported in GISTs, malignant melanomas, hepatocellular carcinomas, cervical carcinomas, and ovarian carcinomas." (PMID 18925963, 2008). "Nevertheless, nestin expression was also detected in rhabdomyosarcomas, gastrointestinal stromal tumors (GISTs), malignant melanomas, hepatocellular carcinomas, cervical carcinomas, and ovarian carcinomas." (PMID 18925963, 2008). "Interestingly, several exclusively mutated genes in murine dormant cells such as ZFPM2, PRKDC, TDRD1, NES, CDC42BPBD and HX57, exhibited moderate to high frequencies of mutation in human melanoma." (PMID 39223638, 2024). "Interestingly, previous research showed that while nestin is strongly upregulated in invasive melanoma, nestin depletion also enhances melanoma invasion in vitro." (PMID 39086667, 2023). "Finally, the evidence that nestin expression level is able to predict therapy response in melanoma has profound clinical implications in the attempt to identify novel biomarkers able to guide clinical decisions in the management of this aggressive disease." (PMID 38008717, 2023). "Interestingly, single cell analyses by mass cytometry have demonstrated that BRAFi and MEKi treatments are able to selectively kill nestin-expressing melanoma cells." (PMID 38008717, 2023). "Finally, we have shown that nestin levels are able to predict response to treatments in melanoma patients." (PMID 38008717, 2023). "Results confirm that nestin high levels are predictive of a better PFS for melanoma patients." (PMID 38008717, 2023). "Lastly, we decided to measure the levels of nestin in in vitro melanoma drug resistant cell lines." (PMID 38008717, 2023). "Moreover, in line with our findings, nestin inhibition has been reported to be sufficient to increase melanoma cell invasiveness in vitro." (PMID 38008717, 2023). "The authors have also accomplished several studies on Nestin and Fascin, and, in this study, one of our aims was to reveal the relationship between Nestin and Fascin and the reason why there are contradicting opinions concerning Fascin expression in melanoma malignancy." (PMID 35054386, 2022). "Nestin and Fascin double-positive melanoma cells were detected." (PMID 35054386, 2022). "In fact, nestin expression has been detected in tumor angiogenesis in several cancer types, including astrocytoma, ependymoma, glioblastoma, melanoma, pancreatic cancer, gastric cancer, colorectal cancer, hepatocellular carcinoma, breast cancer, ovarian cancer, prostate cancer, and lung cancer." (PMID 34943921, 2021). "Few could be markers for melanoma progenitor cells or stem cells, including the neuroepithelial intermediate filament nestin and ATP-binding cassette multidrug transporters." (PMID 35003391, 2021). "Contrastingly, in addition to nestin, SOX2 can successfully distinguish nodal melanocytic nevi from metastatic melanoma and could be a diagnostic tool in melanoma staging." (PMID 35003391, 2021). "Nestin, considered a neural progenitor marker has also been found in extra-neuronal tissues including human solid tumours and has been used as a predictor of poor prognosis in malignant melanoma." (PMID 26356539, 2015). "Upon differentiation, nestin is down-regulated, but its re-expression has been demonstrated in a variety of primary central nervous system (CNS) tumors, in injured tissues of CNS, and in melanoma." (PMID 21383848, 2011). "Similarly, nestin, a neuroepthithelial stem cell marker, is also expressed in greater percentage of melanomas than to benign nevi." (PMID 22545195, 2010). "Nestin expression in stage I and II melanoma patients significantly predict poor survival." (PMID 22545195, 2010). "Our study demonstrated that constitutive expression of YB-1 in melanoma seems to be tightly related to both nestin and vimentin expression which results in a stiffer phenotype, as well as a wide array of proteins involved in RNA, ribosomes, and spliceosome in A375 melanoma cell line." (PMID 39086667, 2023).
melanoma (continued). "Moreover, we asked whether nestin levels may be also predictive of response to targeted therapies in melanoma patients." (PMID 38008717, 2023). "Additionally, we examined the Nestin level in tested melanoma cells." (PMID 33807338, 2021). "Moreover, SOX2-positive melanoma cells tend to be more spindle-shaped and have more peripheral nestin pattern, which may represent a motile, more mesenchymal phenotype." (PMID 29455657, 2018). "Furthermore, stem cell associated markers, nestin and CD133 are highly expressed on circulatory melanoma cells which might represent an index of poor prognosis." (PMID 28137308, 2017). "The survival rates in relation to the high and low mRNA expressions of LOXL3, NES, and SNAI1 in both BRAF-positive (BRAF+) and BRAF-negative (BRAF−) melanoma were analyzed." (PMID 39273022, 2024). "Quantitative cell evaluation of LOXL3, NES, and SNAI1 immunoreactivity in dysplastic nevi, melanoma in situ, and BRAF− and BRAF+ melanoma was performed by determining the section percentage area of the epidermal region." (PMID 39273022, 2024). "We have found co-expression of LOXL3 and SNAI1 in the perinuclear area of all investigated subgroups, and we have also found NES and SNAI1 co-expression in melanoma cells." (PMID 39273022, 2024). "Our study, using two experimental methods, immunofluorescence and qPCR analysis, reports on the aberrant LOXL3, SNAI1, and NES expression and their co-expression in dysplastic nevi, melanoma in situ, and BRAF+ and BRAF– melanoma." (PMID 39273022, 2024). "We found co-expression of LOXL3 and SNAI1 in the perinuclear area of all investigated subgroups and NES and SNAI1 co-expression in melanoma cells." (PMID 39273022, 2024). "Our study, although limited because of the small size of our cohort, provides evidence that the expressions of the investigated markers LOXL3, NES, and SNAI1 change with the progression of melanoma." (PMID 39273022, 2024). "Nestin has been analysed together with CD133 in melanoma, SCCs, and BCCs, and when using Nestin, it was most suitable to differentiate the melanoma subtype." (PMID 31065284, 2019). "In melanoma, different markers have been employed to characterize the putative melanoma CSC and, particularly, CD133, CD271, CD146, ALDH, ABCB5, ABCG2, Nestin and CD117 were considered." (PMID 28125999, 2017). "Analysis of mRNA expression levels of CD271, CD133, ABCB5, SOX2 and melanoma markers SOX10, NES and TYR, MART-1 and MITF-M revealed a strong heterogeneity among the PM tissue samples." (PMID 24799129, 2014). "In fact, in primary melanoma, malignant melanocytes coexpressing FKBP51 and nestin become clearly visible in the intradermal, invasive growth phase; the same double-stained cells formed neoplastic emboli in dermal vessels of skin lesions." (PMID 23559012, 2013). "In advanced melanoma, malignant melanocytes in vascular and perivascular compartments were FKBP51/nestin double positive." (PMID 23559012, 2013). "Higher expression of nestin and CD133 on circulating melanoma cells was suggested as an index of poor prognosis." (PMID 24086245, 2013). "In an experimental model of melanoma metastasis, FKBP51 and nestin were coexpressed in malignant melanocytes that colonized murine organs." (PMID 23559012, 2013). "Although this and additional factors (like JARID1B, NES, NGFR/CD271, SOX10, TDGF1/CRIPTO) have been proposed to mark melanoma CSC (reviewed in 13), the existence of CSC in melanoma tumors remains contentious." (PMID 24098529, 2013). "We found melanoma cells with nuclear FKBP51 and membrane–cytoplasmic nestin in the vertical (invasive, intradermal) growth phase of primary melanomas." (PMID 23559012, 2013). "Several markers of melanoma stem cells have been described in recent studies including CD133, CD166, Nestin and BMI-1." (PMID 22275987, 2008). "Still, it is not easy to distinguish MPNST from desmoplastic melanoma by this marker because they both highly express nestin." (PMID 36831419, 2023).